LINC03040 (long independently transcribed non-coding RNA 3040)
Synonyms: C6orf223; MGC45491
Tractability: PROTAC: ubiquitination databases record sites on it.
Gene: Protein-coding gene on chromosome 6 (44,000,580 to 44,007,612, forward strand). Ensembl gene ENSG00000181577.
Homologues: Orthologues: chimpanzee LINC03040 (96% identical), macaque LINC03040 (88% identical).
Diseases named in the same sentence as LINC03040 in open-access papers:
LINC03040 is named in the same sentence as 9 diseases in open-access papers, as found by Europe PMC text mining. Sharing a sentence is not in itself a finding about the gene and the disease.
LINC03040 shares sentences with these, for which no sentence is quoted: tumor (3 papers); breast carcinoma (1); cancer (1); cervical cancer (1); colorectal cancer (1); herpes infection (1); macular degeneration (1); osteosarcoma (1); prostate carcinoma (1).